PTH (parathyroid hormone)
Diseases named in the same sentence as PTH in open-access papers (continued):
Sharing a sentence is not in itself a finding about the gene and the disease.
adenoma (186 papers, 2005 to 2026). A neoplasm arising from the epithelium. "Our study demonstrated a significant association between adenoma size and PTH-WO levels, particularly highlighting higher levels in adenomas with cystic components or large dimensions." (PMID 41036141, 2025). "The findings of our study indicate that PTH-WO levels are primarily associated with adenoma size and that cystic parathyroid adenomas, compared to solid adenomas, have significantly larger dimensions and higher PTH-WO levels." (PMID 41036141, 2025). "The main cause is a benign tumor of the parathyroid gland (adenoma), leading to excessive and uncontrolled secretion of parathyroid hormone (PTH)." (PMID 39941666, 2025). "The patient had known HBS risk factors: older age, large adenoma, and markedly elevated preoperative calcium and PTH levels." (PMID 41368866, 2025). "The set point for PTH secretion (defined as the concentration of Ca causing half of the maximal inhibition of PTH release) in cells taken from normal glands was found to be lower than in cells taken from adenomas." (PMID 40810066, 2025). "In this setting, the adenoma tends to be larger, associated with higher PTH and calcium levels and significantly worse bone disease." (PMID 39845209, 2024). "pHPT results from excessive release of PTH from the parathyroid glands and is caused in 85–90% of cases by adenoma." (PMID 35407623, 2022). "The established associations between PTH, calcium, phosphate, and adenoma dimensions were further investigated using multiple linear regression." (PMID 33928428, 2021). "Variables significantly associated with adenoma volume were PTH (B = 0.004, p = 0.024) and calcium (B = 5.448, p < 0.001)." (PMID 33928428, 2021). "In the vitamin D deficient subjects PTH level and resected adenoma volume were higher than in patients with sufficient vitamin D level." (PMID 31427650, 2019). "Collectively, these findings suggest that reduced CDKN2B expression was associated with the severity of PHPT as reflected by the adenoma weight and serum PTH levels." (PMID 28600574, 2017). "The bone lesions are the result of a metabolic disorder caused by the altered parathyroid, mainly due to adenomas in 85% of the patients; the overproduction of parathyroid hormones (PTH) causes imbalance in osteoclast activity resulting in bone destruction." (PMID 26881146, 2016). "Tiny adenomas tend to have a low weight and are in general associated with lower preoperative PTH values." (PMID 20844661, 2010). "Our findings indicate that larger adenoma size may be associated with higher preoperative serum PTH levels." (PMID 39941666, 2025). "Higher preoperative calcium and PTH levels are associated with larger adenoma size." (PMID 40104290, 2025). "Additionally, surgical removal of co-occurring adenomas from two parathyroid glands was associated with significantly less frequent normalization of PTH levels on the first day after surgery (11.7% vs. 41.9%; p < 0.05)." (PMID 39941666, 2025). "Primary HPT (PHPT) is an endocrinopathy condition characterized by hypersecretion of PTH, which may be caused by an adenoma (solitary or multiple), idiopathic hyperplasia, or parathyroid carcinoma." (PMID 39213924, 2024). "Parathyroid carcinomas are usually bigger and more metabolically active than adenomas, in a way that most cases are associated with extremely elevated serum calcium and PTH levels (total calcium levels higher than 3.0‐3.5 mmol/L5, 21 and PTH levels at least 10 times higher than normal)." (PMID 32884778, 2020). "In addition, serum PTH levels are associated with adenoma size (> 232 ng/L)." (PMID 41473886, 2026). "In addition to these biological differences, variations in adenoma size and location may also cause significant variability in PTH-WO results." (PMID 41036141, 2025).
adenoma (continued). "Furthermore, we aimed to clarify the role of biochemical markers as predictors of adenoma size by determining associations between preoperative PTH, calcium, and phosphate levels on the one hand, and parathyroid volume on the other using correlation analyses and multiple linear regression." (PMID 33928428, 2021). "Furthermore, cases with inflammatory infiltrates had significantly higher levels of serum PTH as compared to controls (Mann–Whitney U test, P = 0.007), and this association remained significant even after removing the oxyphilic adenomas (n = 14) (Mann–Whitney U test, P = 0.039)." (PMID 28855268, 2017). "The procedure was shown to reduce adenoma size, lower serum PTH and calcium levels, and alleviate symptoms related to the nodules." (PMID 41281376, 2026). "Surgical resection of the adenoma normalized serum calcium and parathyroid hormone levels, leading to marked symptomatic improvement." (PMID 41778164, 2026). "Because parathyroid ultrasound and parathyroid scintigraphy are not very sensitive in diseases affecting multiple glands, like adenomas and hyperplasia, PTH measurement during surgery is used to avoid unsuccessful treatment." (PMID 40104303, 2025). "When the difference in concentration between the jugular PTH was greater than 20%, the side with the highest concentration was according to the location of the adenoma in 100% of the cases." (PMID 40209343, 2025). "PHP diagnosis is defined by high blood calcium and abnormally high PTH levels, and the location of the adenoma is determined using ultrasound or sestamibi scanning." (PMID 41001160, 2025). "Therefore, to maximize the diagnostic accuracy of the PTH-WO test, we believe that it is essential to perform a holistic evaluation of morphological and biological characteristics, such as the embryological origin, vascularity, and anatomical relationship of the adenoma to surrounding tissues." (PMID 41036141, 2025). "In our study, the jugular PTH value was positive in 75.86% of the cases, in addition to the fact that there is a difference between the right and left internal jugular vein PTH values that were unrelated to imaging or adenoma laterality." (PMID 40209343, 2025). "According to multivariate linear regression analysis evaluating variables potentially affecting PTH-WO values, only the long axis of the adenoma emerged as a statistically significant predictor (β = 55; 95% confidence interval [CI]: 0.04–111; p = 0.05)." (PMID 41036141, 2025). "The mean preoperative serum Ca level was 11.21 ± 0.41 mg/dL, the mean preoperative serum P level was 2.3 ± 0.3 mg/dL, and the mean preoperative serum PTH level was 142 ± 89.3 pg/mL in the patients with adenoma." (PMID 40104303, 2025). "For the short axis, PTH-WO values were 815 pg/mL in adenomas ≤ 5 mm and 2,448 pg/mL in those > 5 mm, again showing a significant difference (p = 0.048)." (PMID 41036141, 2025). "A positive correlation was found between the adenoma volumes and the preoperative PTH and calcium levels." (PMID 40104290, 2025). "In order to establish a jugular PTH cutoff value that indicates adenoma laterality, these values were transformed into percentages." (PMID 40209343, 2025). "In this study, adenomas with long axis > 10 mm and short axis > 5 mm had higher PTH-WO levels and showed positive correlation with both dimensions." (PMID 41036141, 2025). "Although ectopic adenomas exhibited higher PTH-WO levels compared to juxtathyroidal adenomas, this difference was on the borderline of statistical significance." (PMID 41036141, 2025). "Although adenoma sizes were similar, plasma PTH levels were higher in men; however, the increase in PTH-WO levels showed only borderline statistical significance." (PMID 41036141, 2025). "The Kruskal-Wallis test demonstrated significantly different PTH level depending on adenoma location (p < 0.001)." (PMID 40445316, 2025).
adenoma (continued). "Some patients, on the foundation of long-term SHPT, as the parathyroid glands are stimulated for a long time, the hyperplastic glands have acquired autonomous function and have developed into adenomas or adenoma-like nodules that secrete PTH independently." (PMID 40510469, 2025). "In adenomas with a long axis greater than 10 mm and those containing cystic components, PTH-WO levels were found to be significantly higher (p = 0.005 and p = 0.02, respectively)." (PMID 41036141, 2025). "The secondary aim was to determine the relationship between actual adenoma volume and preoperative biochemical parameters (PTH and Ca levels)." (PMID 40104290, 2025). "If the expected drop in PTH levels occurs after 10 min post-removal of the single adenoma, the rest of the glands are left untouched and the surgery is considered to be complete." (PMID 40612282, 2025). "In our case, biochemical analysis revealing raised PTH and calcium levels led us to the diagnosis of PHPT, which, as found on further investigations like USG and sestamibi scans, was caused by a single adenoma on the left parathyroid gland." (PMID 40539180, 2025). "The levels of calcium and PTH were highest in patients with cancer-type APTs, followed by those with adenoma-type APTs and then those with adenomas (reference group)." (PMID 40434298, 2025). "In 14 cases the adenoma was on the right side (48.27%) and on the left side in 15 cases (51.27%), and the mean concentration of PTH was 542.9 pg/mL and 69.46 pg/mL on the left and right side, respectively." (PMID 40209343, 2025). "A strong correlation was found between the serum PTH level and the actual adenoma volume (r = 0.723, p = 0.001)." (PMID 40104290, 2025). "Mean preoperative calcium significantly increased with adenoma volume (p < 0.05), as well as mean PTH levels (p < 0.05)." (PMID 39883321, 2025). "Although ectopic adenomas were similar in size to orthotopic adenomas, PTH-WO levels were found to be borderline significantly higher." (PMID 41036141, 2025). "Patients with bilateral adenomas had significantly higher PTH levels compared to those with single adenomas." (PMID 40445316, 2025). "By analyzing the absolute values of the jugular PTH, in the 22 successful cases in identifying adenoma laterality, maximum PTH concentration difference was 2798 pg/mL and minimum 17 pg/mL." (PMID 40209343, 2025). "The median levels of corrected calcium and PTH were 12.6 (11.3–13.9) mg/dL and 800.8 (640.8–865.5) pg/mL, respectively, both higher than in those with adenoma-type APTs (10.9 mg/dL and 134.8 pg/mL, respectively)." (PMID 40434298, 2025). "On the other hand, some studies have failed to confirm this relationship and have even reported higher PTH-WO levels in smaller adenomas." (PMID 41036141, 2025). "Although PTH-WO values were higher in males and in adenomas located ectopically, these differences were borderline significant (p = 0.07 and p = 0.077, respectively)." (PMID 41036141, 2025). "Compared to ultrasonographically measured dimensions, PTH-WO values were significantly higher in adenomas with a long axis of >10 mm and a short axis of >5 mm (p = 0.005 and p = 0.008, respectively)." (PMID 41036141, 2025). "A moderate positive correlation was identified between adenoma size and plasma PTH (ρ = 0.36, p < 0.001)." (PMID 41036141, 2025). "If the sestamibi scan was unable to correctly identify both adenomas when 2 were found at surgery, then this was determined an unsuccessful localisation with regards to preoperative PTH, calcium and 25-hydroxyvitamin D analysis." (PMID 40979160, 2025). "Our secondary aim was to determine the relationship between adenoma volume and preoperative biochemical parameters (parathyroid hormone [PTH] and calcium levels)." (PMID 40104290, 2025). "Previous studies have demonstrated a positive correlation between preoperative PTH level and removed adenoma volume." (PMID 40810066, 2025).
adenoma (continued). "Our binary logistic regression analysis investigates the predictors of fracture presence using age, adenoma size, PTH level, albumin-corrected calcemia, and 25(OH)D level as covariables." (PMID 39040613, 2024). "Significant associations were observed between SWV values and serum calcium, parathyroid hormone (PTH), and adenoma size within the patient group (P < 0.001, P < 0.001, P = 0.016, respectively)." (PMID 38280162, 2024). "In the patient group, there was a significant correlation between serum calcium, PTH, and adenoma size with the SWV values (r = 0.573; P < 0.001, r = 0.634; P < 0.001, r = 0.412; P = 0.01, respectively)." (PMID 38280162, 2024). "The mean duration of the surgical procedure until adenoma excision was 44.7 min (SD ± 25.2 min), while the mean duration of the entire procedure (including waiting for the result of the last intraoperative PTH value) was 85.5 min (SD ± 37.1 min)." (PMID 39682204, 2024). "Based on our findings, we suggest using both PTH levels and PFi as an indicative marker for adenoma size prediction." (PMID 39040613, 2024). "They proposed a formula for predicting adenoma weight based on preoperative calcium-PTH levels and age." (PMID 39040613, 2024). "We also found a positive correlation between PTH and adenoma size, the parathyroid function index and adenoma size, as well as PTH and phosphate levels." (PMID 39040613, 2024). "The main treatment for PHPT is surgical removal of the adenoma, which normalizes PTH levels and terminates the progression of bone disease and leads to its regeneration." (PMID 39519190, 2024). "PTH levels drop immediately after removing one adenoma, and long-term suppression of the other glands ceases bone resorption." (PMID 39152506, 2024). "When SVS correctly lateralized the pathological gland, the PTH gradient was observed to be 1.5–2 times higher than the normal PTH level, providing valuable guidance for localizing the adenoma within the specific anatomical quadrant of the neck." (PMID 38541233, 2024). "The patient underwent minimally invasive parathyroidectomy, with a significant intraoperative decrease of PTH after removal of the adenoma." (PMID 39845209, 2024). "Intra-operative PTH (ioPTH) monitoring confirmed the excision of the adenoma as the PTH dropped from 4950 pmol/L (pre-excision) to 618 pmol/L (30′ after excision)." (PMID 36334246, 2023). "Since we cannot predict the PTH level in the adenoma, a level based on a positive cut-off value or based on dilution would not be appropriate in most cases of PHPT." (PMID 37745742, 2023). "The current study which encompassed the MIBI positive entire group also demonstrated that the ratio of PTH/Svol was lower in larger volume adenomas." (PMID 37892003, 2023). "Compared to the adenoma group, patients with PC had higher levels of PTH, ionized and total calcium, ALP, creatinine, and the lower GFR." (PMID 37465121, 2023). "It is a condition in which the (hyperplastic) parathyroid glands or adenoma of the parathyroid produce excessive amounts of parathyroid hormone (PTH), leading to an imbalance in calcium and phosphorus metabolism." (PMID 37627135, 2023). "What favors the diagnosis of adenoma is the fact that normalization of PTH was observed in all patients after removal of the only cystic parathyroid gland." (PMID 37568342, 2023). "On the other hand, it has been expressed that adenoma weight and serum PTH concentrations were also significant predictors for MIBI positivity." (PMID 37892003, 2023). "As can be expected, mean serum levels of Ca, AP, and PTH were higher and serum P and 25-hydroxyvitamin D levels were lower in patients with larger adenomas with significant difference within and between cohorts when compared to the smaller adenomas." (PMID 36817587, 2023). "Previous studies have reported a significant relationship between MIBI positivity and adenoma volume with calcium and PTH levels." (PMID 37892003, 2023).
adenoma (continued). "Adenoma volume (Svol) and parathormone (PTH)/Svol ratio were measured as SPECT/CT-derived parameters." (PMID 37892003, 2023). "The blood PTH concentration in the adenoma group was significantly higher than that in the hyperplasia group." (PMID 37713846, 2023). "When an adenoma overproduces parathyroid hormone (PTH), it can disrupt the normal balance of calcium and phosphate, leading to ricket-like manifestations." (PMID 37790151, 2023). "We also reported the potential role of calcium and vitamin D nutrition on serum PTH levels and adenoma weights from different parts of the world." (PMID 36817587, 2023). "There was a concordance between preoperative and postoperative PTH concentration, the higher the preoperative PTH, the lower the postoperative PTH after removal of the adenoma (p < 0.01)." (PMID 36268338, 2022). "She underwent anterosuperior mediastinal ectopic PTH-producing cyst-like tumor resection (suspect of thymic cyst and/or adenoma, parathyroid cyst and/or adenoma)." (PMID 36544116, 2022). "Most surgeons advocate the use of two localization investigations to detect the position of adenomas and almost all advocate the use of intraoperative PTH monitoring." (PMID 36237812, 2022). "On the other hand, we found that PTH was on average significantly higher in adenomas detected than in those missed by 99mTc-MIBI-SPECT, confirming the findings of Mihai and Khorasani16,22." (PMID 36261462, 2022). "The guidelines from the German association of endocrine surgeons for the management of primary and renal hyperparathyroidism strongly recommends (consensus ++) the intraoperative PTH measurement for focused procedures when adenoma is preoperatively localized." (PMID 35407623, 2022). "In patients with single adenomas, pre-operative PTH-levels were higher when the adenoma was detected by 99mTc-MIBI-SPECT than when it was not (p = 0.02)." (PMID 36261462, 2022). "Low PTH serum levels and ionized calcium, a small adenoma, multiglandular disease and/or concomitant thyroid disease represent some factors associated with a lower scintigraphy performance." (PMID 33669104, 2021). "Based on the multivariable regression model, adenoma volume can be estimated using the following algorithm: volume = – 13.657 + 0.004*PTH + 5.448*calcium – 1.308*phosphate – 0.014*age + 0.041*BMI." (PMID 33928428, 2021). "The second confusing point was that after the first adenoma excised, quick intraoperative PTH assay revealed a reduction in PTH levels more than 50% from the preoperative level, which was indicative of biochemical cure." (PMID 33845885, 2021). "Adenoma volume was positively correlated with preoperative PTH (p < 0.001) and calcium (p < 0.001) and negatively correlated with preoperative phosphate (p = 0.001)." (PMID 33928428, 2021). "Complementary tests disclosed elevated blood level of parathyroid hormone and a partially cystic enlarged left inferior parathyroid gland consistent with adenoma." (PMID 34034731, 2021). "Ten minutes after the excision of the suspected adenoma, a blood sample was taken and the intact PTH level dropped and was within normal range (49.30 pg/ml), indicating a reduction of more than 50% from the preoperative level." (PMID 33845885, 2021). "In 2018, a retrospective study of 52 patients highlighted a strong positive correlation between the SUVmax and the PTH level as well as between the adenoma-to-background ratio and the PTH level on both late and early phases." (PMID 33669104, 2021). "It is usually attributable to a coexisting parathyroid hyperplasia or adenoma, rarely being non-PTH-dependent." (PMID 33933067, 2021). "Calcium and parathyroid hormone (PTH) levels are typically much higher in cases of parathyroid carcinomas compared to adenomas." (PMID 35173680, 2021). "Intraoperative PTH (IOPTH) assays are a widely used method for intraoperative adenoma verification with excellent overall operative success rates of 97–99%." (PMID 33928428, 2021).